ASGR2 (asialoglycoprotein receptor 2)
Description:
Mediates the endocytosis of plasma glycoproteins to which the terminal sialic acid residue on their complex carbohydrate moieties has been removed. The receptor recognizes terminal galactose and N-acetylgalactosamine units. After ligand binding to the receptor, the resulting complex is internalized and transported to a sorting organelle, where receptor and ligand are disassociated. The receptor then returns to the cell membrane surface.
Synonyms: HL-2; CLEC4H2; ASGP-R2; ASGPR2; HBXBP
Tractability: Antibody: its Gene Ontology location is reachable by antibodies, with high confidence; UniProt predicts a signal peptide or a membrane-spanning region; the Human Protein Atlas places it where antibodies can reach. PROTAC: its protein half-life has been measured.
Gene: Protein-coding gene on chromosome 17 (7,100,166 to 7,116,603, reverse strand). Ensembl gene ENSG00000161944.
Subcellular location: Membrane
Subcellular location (Human Protein Atlas): Endoplasmic reticulum; Plasma membrane
Pathways (Reactome):
Metabolism of proteins: Asparagine N-linked glycosylation
Gene Ontology:
Molecular function: protein binding; asialoglycoprotein receptor activity; D-mannose binding; fucose binding; pattern recognition receptor activity
Biological process: cell surface receptor signaling pathway; immune response; vesicle-mediated transport
Cellular component: endoplasmic reticulum quality control compartment; perinuclear region of cytoplasm; plasma membrane; external side of plasma membrane; membrane
Genetic constraint (gnomAD): Loss-of-function variants: 35 observed, 33.99 expected, observed/expected ratio (o/e) 1.03, 90% interval 0.79 to 1.37. The upper end of that interval is the gene's LOEUF score, 1.37, which puts it in group 5 of 6, group 1 being the genes least tolerant of losing a copy. Missense variants: 385 observed, 400.75 expected, observed/expected ratio (o/e) 0.96, 90% interval 0.88 to 1.04. Synonymous variants: 143 observed, 155.06 expected, observed/expected ratio (o/e) 0.92, 90% interval 0.8 to 1.06.
Homologues: Orthologues: chimpanzee ASGR2 (99% identical), macaque ASGR2 (93% identical), pig ASGR2 (68% identical), guinea pig ASGR2 (67% identical), mouse Asgr2 (65% identical), rabbit ASGR2 (63% identical), rat Asgr2 (62% identical), dog ASGR2 (61% identical), Drosophila melanogaster tfc (19% identical), Caenorhabditis elegans clec-266 (17% identical), Caenorhabditis elegans clec-87 (14% identical), Caenorhabditis elegans clec-88 (14% identical), and 6 more. Paralogues in human: ASGR1 (56% identical), CLEC10A (46% identical), CLEC4E (21% identical), FCER2 (21% identical), CLEC4A (20% identical), CLEC4F (20% identical), CD209 (20% identical), CLEC17A (19% identical), CLEC4M (19% identical), CD207 (19% identical), CLEC6A (19% identical), CLEC4D (18% identical), and 2 more.
Diseases named in the same sentence as ASGR2 in open-access papers:
ASGR2 is named in the same sentence as 17 diseases in open-access papers, as found by Europe PMC text mining. Sharing a sentence is not in itself a finding about the gene and the disease. The quoted sentences say what the papers report.
gastric cancer (6 papers, 2021 to 2025). A primary or metastatic malignant neoplasm involving the stomach. "ASGR2 enhances tumor survival and metastasis, with higher levels linked to poor prognosis in gastric cancer." (PMID 41378310, 2025). "We showed that PS exposure causes ASGR2 gene alterations associated with gastric cancer." (PMID 35547772, 2022). "Thus, while the amount of MP exposure used in this study is greater than current real world exposure levels, it is suggested that continuous and repetitive MP exposure is likely to cause ASGR2 gene alterations related to gastric cancer, as presented in this study." (PMID 35547772, 2022). "In gastric cancer, polystyrene exposure associated with higher CD44 and ASGR2, aligning with stemness/adhesion and glycoprotein handling." (PMID 41378310, 2025). "In gastric cancer, ASGR2 contributes to the manifestation of cancer hallmarks upon PS exposure and confers resistance to both chemotherapy and monoclonal antibody-based therapies." (PMID 41158511, 2025). "Increased ASGR2 was closely associated with poorer prognoses, EMT, and proliferation in gastric cancer." (PMID 35547772, 2022). "Conversely, MP exposure has also been shown to increase the expression of asialoglycoprotein receptor 2 (ASGR2), which is associated with gastric cancer and multidrug resistance to chemotherapy, due to the upregulation of CD44 expression observed in vitro and in vivo after four weeks of exposure." (PMID 40559911, 2025). "Studies report that MPs can upregulate efflux transporters (ABCB1/ABCG2) and alter chemotherapeutic susceptibility, enhance metastatic features in breast cancer, promote therapy resistance via ASGR2 in gastric cancer, and aggravate radiation-induced intestinal injury." (PMID 41378310, 2025). "Upregulation of ASGR2 in gastric cancer matches our predicted targeting by miR-760." (PMID 41378310, 2025). "Transcriptomics Identified ASGR2 as a predictor of hematogenous recurrence of gastric cancer." (PMID 35547772, 2022). "According to our findings, ASGR2, Bax, CD44, and TIM4 are genes impacted by MPs in gastric cancer cells." (PMID 41378310, 2025). "For instance, miR-302c-3p targets TIM4 in cervical cancer, miR-144 targets MUC2 in colorectal cancer, miR-706 and miR-665 target ASGR2 and CD44 in gastric cancer, and miR-532-3p and miR-593-5p target MAPK genes in lung cancer." (PMID 41378310, 2025). "The molecular mechanism behind this effect involved the increased expression of CD44, a cancer stem cell marker in numerous human solid tumors, and subsequent upregulation of asialoglycoprotein receptor 2 (ASGRA2), which acts as an oncogene in gastric cancer." (PMID 41154647, 2025). "In gastric cancer, miR-665 and miR-760 targeted CD44 and ASGR2; in liver cancer, miR-638 showed broad predictions (e.g., HO-1, PPARα/γ)." (PMID 41378310, 2025). "Finally, we found that the imbalance of 11 immune regulatory factors could predict the overall survival time of gastric cancer, including EZH2, NRP1, CD59, OsBPL1aBCL11B, BASP1, HNMT, CXCR4, ASGR2, ANXA5, CDH2." (PMID 34322132, 2021).
cervical cancer (2 papers, 2023 to 2025). A primary or metastatic malignant neoplasm involving the cervix. "The enriched genes included CD4 in cervical cancer, VPS52, NUP62, CRYGD, IL34, GATA3 in prostate cancer and F11, TXNIP, KIT, ASGR2, SERPINF1 in liver cancer, which also provide insight into the molecular mechanisms underlying cancer progression and the potential impact on patient survival." (PMID 37393582, 2023).
chronic thromboembolic pulmonary hypertension (2 papers, 2024 to 2025). Chronic thromboembolic pulmonary hypertension (CTEPH) is characterized by the persistence of thromboemboli in the form of organized tissue obstructing the pulmonary arteries. "A recent study indicated that serum ASGR2 levels could serve as a biomarker for assessing the therapeutic effects of balloon pulmonary angioplasty (BPA) in patients with chronic thromboembolic pulmonary hypertension (CTEPH)." (PMID 41158511, 2025).
hepatocellular carcinoma (2 papers, 2022 to 2025). A malignant tumor that arises from hepatocytes. "ASGR2 expression correlates significantly with the clinical stage of hepatocellular carcinoma." (PMID 41158511, 2025).
candidiasis (1 paper, 2021). Infection with the organism Candida. "Interestingly, we showed that genetic variation in close vicinity of the phagocytosis/phagosome maturation-associated genes ASGR2, LAMP1, RAB42, GEM, ATP6V1B2, and RAB20 are associated with susceptibility to candidiasis." (PMID 33510868, 2021).
glioblastoma (1 paper, 2026). The most malignant astrocytic tumor (WHO grade IV). "ASGR2 and CLEC12A expression was also validated by cytofluorimetric analysis on both tumor and liquid biopsies from 20 glioblastoma patients." (PMID 41898489, 2026).
hepatoblastoma (1 paper, 2012). Hepatoblastoma (HB) is a malignant hepatic tumor and is the most common pediatric liver cancer. "Hepatoblastoma overexpresses ASGR1 asialoglycoprotein receptor 1, and ASGR2." (PMID 23251904, 2012).
pulmonary fibrosis (1 paper, 2025). Chronic progressive interstitial lung disorder characterized by the replacement of the lung tissue by connective tissue, leading to progressive dyspnea, respiratory failure, or right heart failure. "Additionally, these results also suggest the possible association between the specifically co-expressed genes such as Ccl22, Asgr2, and Slc27a3, and pulmonary fibrosis." (PMID 40269953, 2025).
viral infection (1 paper, 2024). "Furthermore, genetic depletion of several other factors, such as ASGR1, ASGR2, and ST6GAL1, also impaired viral infection, albeit with a 10–20% reduction." (PMID 39173055, 2024).
cancer (6 papers, 2010 to 2025). A tumor composed of atypical neoplastic, often pleomorphic cells that invade other tissues. "Then enhanced ASGR2 induced typical cancer hallmarks such as proliferation, N-cadherin, CD44, PD-L1 for both in vitro and in vivo." (PMID 35547772, 2022). "Especially, we identified ASGR2 as the messenger of PS-mediated changes in cancer hallmarks." (PMID 35547772, 2022). "We showed that cancer stemmess (CD44+ in this study) 18, 19, 52, 53 increased by PS exposure through ASGR2." (PMID 35547772, 2022).
tumor (5 papers, 2010 to 2026). "We report that ASGR2 and CLEC12A C-type lectins are associated with tumor-infiltrating immunosuppressive myeloid subsets and discriminate patients' poor prognosis." (PMID 41898489, 2026).
ASGR2 also shares sentences with these, for which no sentence is quoted: liver cancer (2 papers); bacterial infections (1); chronic obstructive pulmonary disease (1); colorectal cancer (1); lung carcinoma (1); prostate carcinoma (1).